CD36 (CD36 molecule (CD36 blood group))
Diseases named in the same sentence as CD36 in open-access papers (continued):
Sharing a sentence is not in itself a finding about the gene and the disease.
breast carcinoma (continued). "Inhibition of CD36 expression by siRNA or dysfunction of CD36 by antibody reduced breast cancer cell growth, which suggests that the modulation of CD36 expression might be a potential therapeutic approach to enhance tamoxifen therapeutic effect on tumors." (PMID 30573731, 2018). "To determine the correlation between the prognosis of breast cancer and the CD36 expression levels, we retrieved CD36 messenger RNA (mRNA) expression data from the gene-expression profiling dataset (#206488 in Kaplan–Meier Plot database), and completed the Kaplan–Meier analysis on the dataset." (PMID 30573731, 2018). "Relative mRNA expression levels of FABP4, FABP5 and CD36 in breast cancer cell lines." (PMID 29914512, 2018). "Because SLC27A4 is a transmembrane protein, blockage of extracellular SLC27A4 via a SLC27A4 antibody might be a novel therapeutic strategy against breast cancer due to disruption of the SLC27A4/CD36-mediated fatty acids transportation pathway." (PMID 30388870, 2018). "The effects of CD36 on proliferation/migration of breast cancer cells and tamoxifen-inhibited ER-positive cell growth are unknown." (PMID 30573731, 2018). "However, the exact role of CD36 in tumorigenesis, particularly in breast cancer, needs more investigation." (PMID 30573731, 2018). "Indeed, high expressing CD36 attenuated inhibition of breast cancer cell growth by tamoxifen, while inhibition of CD36 synergized tamoxifen-induced cell death, which is associated with regulation of ERK1/2 activity correspondingly." (PMID 30573731, 2018). "Clinically, the presence of CD36+ metastasis-initiating cells correlates with a poor prognosis for different carcinomas, and inhibition of CD36 also affects metastasis, at least in human melanoma- and breast cancer-derived tumors." (PMID 29167646, 2017). "Further studies are required to know why CD36 is downregulated in CE-rich breast cancer carcinomas." (PMID 26055977, 2015). "Conversely, CD36 mRNA expression in breast cancer is inversely correlated with the metastatic potential of five breast cancer cell lines, where its expression is relatively higher in less aggressive cell lines (T47-D and MCF-7) and almost absent in highly aggressive lines (ZR-75 and MDA-MB-231)." (PMID 25866768, 2015). "Therefore, the previous results exhibited that CD36 might participate in proliferation, migration and tamoxifen-inhibited growth of ER-positive breast cancer cells." (PMID 39920872, 2025). "Since lipid metabolic remodeling as an emerging mechanism participate in resistance to kinase inhibitors, we hypothesize that the inhibition of SCD-1 or CD36 might potentiate the effects of current PI3K-targeting agents in breast cancer with resistance to anti-HER2 drugs." (PMID 39920872, 2025). "Therefore, elevated levels of CD36, AQP7, LIPE, and AKR1C1 in mammary epithelial cells may serve as promising indicators for identifying high-risk breast cancer groups." (PMID 40868150, 2025). "The addition of a CD36 inhibitor might boost the anti-proliferation effects of PI3K therapeutics in anti-HER2 resistant, PTEN-loss breast cancer cells, thus providing promising insights for the development of combination regimens based on approved PI3K inhibitors with a tolerable toxicity profile." (PMID 39920872, 2025). "Therefore, utilising the tamoxifen-CD36 inhibitor combination might require stratifying breast cancer patients based not only on tamoxifen resistance, but also on both CD36 and ER expression levels." (PMID 35448537, 2022). "Given oestradiol induces proliferation and downregulates CD36 in several breast cancer cell lines, a mechanism similar to this might also be operating in breast cancer, suggesting oestradiol could promote the malignancy of breast cancer in a CD36-dependent manner, by downregulating MEDA-4." (PMID 35448537, 2022). "Thus, we extensively explored the role of CD36 in adipocyte-breast cancer cell interaction." (PMID 34561446, 2021).
breast carcinoma (continued). "Indeed, Cd36 expressing fibroblasts counteract breast cancer cell growth in an organoid co-culture model by triggering the expression and release of unknown paracrine factors by fibroblasts." (PMID 33876316, 2021). "To determine if increased CD36 expression results in metabolic changes, we used the GO-lipid metabolic process gene list present in the molecular signature database (MSigDB) to generate a correlation matrix for increased CD36 expression in the TCGA breast cancer patient dataset." (PMID 34561446, 2021). "Thus, CD36 may serve as an important regulatory factor mediating reprogramming of fatty acid metabolism in breast cancer cells." (PMID 35071325, 2021). "Hence, by identifying factors secreted by CD36+ FBs, an improved therapeutic approach may be elucidated for breast cancer therapy." (PMID 34572749, 2021). "Furthermore, studies have found the high CD36 expression in breast cancer cells." (PMID 33180852, 2020). "To determine if CD36 expression is involved in proliferation or migration of breast cancer cells in an ER-dependent manner and influence the effect of tamoxifen on cell growth, we selected four types of breast cancer cell lines, MCF-7, ZR-75-30, MDA-MB-231 and T-47D cells." (PMID 30573731, 2018). "Only one study has shown CD36 as a direct binding partner of FABP4, facilitating fatty acid transfer from adipocytes to breast cancer cells." (PMID 41392988, 2025). "Therefore, CD36 might serve as a potential target to treat resistant HER2-positive breast cancer." (PMID 39920872, 2025). "This is achieved by recruiting the SWI/SNF complex and HDAC1 to transcriptionally repress CD36 and FABP4 expression in breast cancer cells." (PMID 40002245, 2025). "Further studies will focus on gaining a more detailed understanding of why the reprogramming of FA uptake induces plasticity in HER2 + mammary tumor cells, leading to the intratumor enrichment of EMT-like CD36+ /HER2 + cancer stem cells (CSCs)." (PMID 39833955, 2025). "Recent investigations have provided evidence of FABP4, CD36, and ANGPTL4, proteins involved in the release, uptake, and intracellular handling of triglycerides and fatty acids, in breast cancer pathology." (PMID 39456610, 2024). "Moreover, CD36 overexpression might correlate with poor clinical outcomes in human breast cancer." (PMID 37174034, 2023). "In this experiment, CM from breast cancer cell lines suppressed PPARγ and its target genes FABP4 and CD36 in both ECs and pericytes compared to CM from HMECs." (PMID 37816052, 2023). "The fatty acid receptor CD36 is overexpressed in many metastatic tumors, such as oral squamous cell carcinomas (OSCC), melanoma and breast cancers." (PMID 36670988, 2023). "Oncoprint analysis showed genetic alterations in FABP4 (14%), ADIPOQ (2.9%), PPARG (2.8%), PPARGC1A (1.5%), CD36 (1.7%), and CREBBP (11%) in patients with breast cancer in a TCGA study." (PMID 36114448, 2022). "Inhibition of CD36 and FABP4 induces apoptosis in breast cancer cells and inhibits the growth of mouse xenografts." (PMID 36532833, 2022). "Oncoprint analysis revealed genetic alterations in FABP4 (14%), ADIPOQ (2.9%), PPARG (2.8%), PPARGC1A (1.5%), CD36 (1.7%), and CREBBP (11%) in patients with breast cancer in a TCGA study." (PMID 36114448, 2022). "Oncoprint analysis revealed genetic alterations in FABP4 (14%), ADIPOQ (2.9%), PPARG (2.8%), PPARGC1A (1.5%), CD36 (1.7%), and CREBBP (11%) in patients with breast cancer in the TCGA study." (PMID 36114448, 2022). "Nur77 recruits SWI/SNF complex and HDAC1 to suppress the transcription of CD36 and FABP4, hampering breast cancer cells uptake of exogenous FAs and leading to the inhibition of cell proliferation." (PMID 35899119, 2022). "CD36 expression promotes breast cancer by increasing STAT3 signaling and beta oxidation, providing energy for growing breast cancer cell." (PMID 35888767, 2022).
breast carcinoma (continued). "This study explored the potential targets of RGZ as antiangiogenic agents in breast cancer therapy and highlighted FABP4, ADIPOQ, PPARG, PPARGC1A, CD36, and CREBBP as potential targets of RGZ." (PMID 36114448, 2022). "DNA methylation analysis revealed that the predictive significance of FABP4, ADIPOQ, PPARG, PPARGC1A, CD36, and CREBBP in a specific CpG was significant in the emergence of breast cancer." (PMID 36114448, 2022). "We demonstrated a heatmap and prognostic value of DNA methylation clustering of the expression levels of FABP4, ADIPOQ, PPARG, PPARGC1A, CD36, and CREBBP in breast cancer." (PMID 36114448, 2022). "For example, FAs released from adipocytes are transported into breast cancer cells via CD36, which in turn induces EMT and stem cell properties in breast cancer cells by activating STAT3 signaling." (PMID 36354702, 2022). "For example, in breast cancer tissues with high mammographic density, the lower adipocyte content and higher stromal cell and extracellular matrix content were associated with the absence of CD36 expression in CAFs, and the lower CD36 expression was associated with greater tumor aggressiveness." (PMID 36354702, 2022). "The correlation between increased CD36 expression and EMT markers was also present in the breast cancer cohorts." (PMID 34561446, 2021). "We also found that breast cancer cells induce the transcription of different fatty acid transporters such as FABP4, FABP5 and CD36." (PMID 34884983, 2021). "To validate the functional effect of CD36-induced fatty acid uptake on enhanced FAO and metabolic reprogramming in breast cancer cells, we assessed the metabolic changes following culturing with adipocyte-conditioned media, using the Seahorse XF24 analyser." (PMID 34561446, 2021). "Next, we determined the correlation between increased CD36 expression and the various FABP genes (FABP1, FABP2, FABP3, FABP4, FABP5 and FABP6) in the TCGA breast cancer cohort." (PMID 34561446, 2021). "The role of CD36 in promoting adipocyte-induced EMT and stemness indicates a direct role in adipocyte-induced breast cancer cells aggressiveness." (PMID 34561446, 2021). "To investigate the role of CD36 S-acylation in LCFA uptake by cancer cells, we used a murine breast carcinoma cell line." (PMID 34314388, 2021). "We used the TCGA breast cancer cohort to interrogate the correlation between increased CD36 expression and EMT markers in clinical breast cancer patients." (PMID 34561446, 2021). "Breast cancers have increased expression of fatty acid-binding proteins (FABP3, FABP7 or FABP4) and CD36, which are involved in the uptake and subcellular trafficking of fatty acids." (PMID 33808259, 2021). "Perhaps the most intriguing finding from our study was that CL-TNBC, specifically, had much higher expression of CD36, LPL, PDGFRB, FABP4, and PDK4 compared to all other breast cancers, including basal-TNBC." (PMID 31942031, 2020). "Analysis of The Cancer Genome Atlas (TCGA) showed that AKR1C1, AQP7, CD36, and LIPE display low genomic alteration frequency in breast cancer, and only CD36 expression has prognostic value (P = 0.005)." (PMID 33083529, 2020). "We created a “fatty acid metabolism gene signature” consisting of CD36, LPL, PDK4, and FABP4 and checked each molecular subtype of breast cancer for upregulation or amplification of these genes." (PMID 31942031, 2020). "Similar to CD36, PDK4 and FABP4 are also highly expressed in CL breast cancers compared to all other molecular subtypes with the exception of normal-like breast tumours." (PMID 31942031, 2020). "CD36 and AQP7, which mediate the transport of fatty acids and water/glycerol, respectively, are expressed in tumors including breast cancer and are involved in cell migration and tumor metastasis." (PMID 33083529, 2020).
breast carcinoma (continued). "When breast cancer cells are cultured with adipocytes in a cell line study, lipid droplets accumulate within cancer cells, and expression levels of FABP4, CD36 and perilipin 2, molecules that play roles in lipid transfer, are increased." (PMID 32674405, 2020). "In breast cancer, apoptotic tumor cells release miR-375 and bind LDL, and this mediates their uptake by TAMs through CD36." (PMID 31410189, 2019). "Currently, the role of SLC27 family proteins is not fully understood in breast cancer although the role of ACSL, FABP, and CD36 has been investigated." (PMID 30388870, 2018). "According to an IHC investigation, the significant downregulation of CD36 in ER-, PR-, HER2+, TNBC, and basal-like breast cancer may suggest a shift in metabolic and tumor microenvironmental dynamics." (PMID 40565366, 2025). "Interestingly, elevated levels of CD36 have been identified in intra-tumor regulatory Treg cells in patients with melanoma, non-small cell lung cancer (NSCLC), and breast cancer." (PMID 39624081, 2024). "Interestingly, CD36 was also found to be elevated in tamoxifen-resistant MCF7 cells, which is a HER2- breast cancer cell line." (PMID 37371076, 2023). "In a breast cancer murine model, diet-induced obesity activates the Lysophosphatidic acid/protein kinase D (PKD-1) signaling pathway, downregulating CD36 expression in the tumor endothelium, which could be a key step in initiating the microvascular remodeling." (PMID 36568966, 2022). "Additionally, CsnB also acts as a candidate to downregulate CD36/FABP4 expression, leading to the inhibition of fatty acid uptake and consequent breast cancer cell proliferation in NR4A1-dependent manner." (PMID 36052242, 2022). "On the contrary, SIRT1 overexpression by resveratrol (a classical activator of sirtuins) was reported to increase the expression of CD36 (a transmembrane receptor that regulates apoptosis and angiogenesis) to cytotoxic levels, thus inhibiting the proliferation of MCF-7 breast cancer cells." (PMID 36291902, 2022). "The inhibition of CD36 and FABP4 induces apoptosis in breast cancer cell lines." (PMID 35888767, 2022). "In the present study, we show that each of the three ligands could also reprogram CAFs and induce their transdifferentiation by overexpressing CD36 and FABP4 while strongly suppressing the growth of breast cancer cells." (PMID 36361532, 2022). "Nevertheless, more studies are needed to unravel, in breast cancer pathogenesis, the mechanism linking oestradiol-regulated MEDA-4 and CD36, specifically its FA-uptake role, given its multifaceted properties of being both pro- and anti-carcinogenic, through a multitude of mechanisms." (PMID 35448537, 2022). "Similarly, CD36 and FABP4 inhibition significantly decreased the proliferative, migratory, and invasive abilities of breast cancer cells." (PMID 34561446, 2021). "However, inhibiting both CD36 and FABP4 significantly decreased the breast cancer cell viability over 72 h." (PMID 34561446, 2021). "Thus, CD36 was inhibited, with SSO, and FABP4, with BMS309403, and their effects on breast cancer cells determined." (PMID 34561446, 2021). "CD36 expression, either at protein or mRNA level, is highest in MCF-7 cells, while being lowest in MDA-MB-231 cells, indicating the sensitivity of tamoxifen to growth of breast cancer cells is related to cellular CD36 expression." (PMID 30573731, 2018). "It implies that uptake of palmitic acid or other types of fatty acid is not fully dependent on CD36 in breast cancer." (PMID 30388870, 2018). "RT-qPCR of select cancer-related genes in both shRING1B T47D and MDA-MB-231 cells confirmed the RNA-seq results, and further suggested that fatty acid metabolism (represented by CD36 and HMGCS2) may play a major role in the tumorigenesis of ER+ breast cancer." (PMID 30139998, 2018). "Despite the capacity of CD36 to bind native and modified lipoproteins, CD36 does not seem to contribute to intratumor CE accumulation in breast cancer." (PMID 26055977, 2015).
breast carcinoma (continued). "Overexpression of CD36 did not induce ferroptosis in estrogen receptor positive breast cancer." (PMID 41672971, 2026). "The present in vitro study explores the presence of fusion between the monocyte cell line (THP-1) and the breast cancer cell line (MCF-7) in relation to the expression of CD36 and phosphatidylserine with and without treatment of these cells with ionizing radiation." (PMID 39752516, 2025). "In summary, our study revealed that CD36 expression is decreased in TNBC and that higher CD36 expression correlates with improved prognosis in TNBC patients, suggesting that CD36 may function as a tumor suppressor in this subtype of breast cancer." (PMID 41267927, 2025). "CD36 can maintain lipid homeostasis via the modification with palmitoylation which might facilitate MUFA uptake, decrease saturation-lipotoxicity and contribute to high-fat-diet-driven metastasis in breast cancer mouse models." (PMID 39920872, 2025). "However, fatty acid transporters such as CD36, FATP3, and FATP4 were undetectable in the breast cancer cell lines used (unpublished observations), indicating that their expression level in breast cancer cells likely had minimal contribution to FASN regulation of p65 expression." (PMID 38467328, 2024). "Furthermore, JC63.1C, an anti-CD36 monoclonal antibody, was found to resensitize lapatinib-resistant xenograft tumors to HER2-targeted therapy, providing a novel direction for combinatorial treatment strategies in breast cancer." (PMID 37700339, 2023). "This study suggests that CD36-mediated therapy resistance may not be specific to the HER2+ subtype of breast cancers." (PMID 37371076, 2023). "Since CD36 is overexpressed in CTCs after culture, they may have a greater potential to generate CDX in vivo, taking into account the suggestion that CD36 mediates migration and invasion capacity in breast cancer." (PMID 34071445, 2021). "To assess whether CD36 is required for LCFA uptake, we used a murine breast carcinoma cell line, 4T1.2, in which glycosylated CD36 was not detectable." (PMID 34314388, 2021). "Indeed the aggressive “triple-negative” breast cancer cell lines express lipoprotein lipase (LPL), the key enzyme for extracellular lipolysis, and the transmembrane channel for exogenous free FA uptake (CD36), together with the classical lipogenic markers such as FASN." (PMID 26452259, 2015). "Furthermore, CD36 in interaction with FABP4 that enhance the import of free fatty acids from adipocytes in the tumor microenvironment leads to activation of STAT3 signaling, metabolic reprogramming with a shift toward beta oxidation and promoting breast cancer progression." (PMID 39920872, 2025). "More than ten years later, Feng and colleagues discovered that breast cancer cells could escape lapatinib (an oral dual tyrosine kinase inhibitor that targets epidermal growth factor receptor-EGFR and HER2) and consequently survive by displaying a change toward CD36-mediated FA uptake 61,69." (PMID 38370376, 2024). "Thus, CD36-induced activation of the ERK1/2 and STAT3 signalling pathways in the adipocyte environment may account for the enhanced proliferation, migration and invasion of breast cancer cells." (PMID 34561446, 2021). "The mRNA levels of FABP4, ADIPOQ, PPARG, CD36, and PPARGC1A were significantly lower in patients with breast cancer than in those without breast cancer." (PMID 36114448, 2022). "The mRNA expression levels of FABP4, ADIPOQ, PPARG, CD36, and PPARGC1A were significantly lower in patients with breast cancer, whereas the mRNA levels of CREBBP were not different between patients with breast cancer and normal breast tissues." (PMID 36114448, 2022).